KIT (KIT proto-oncogene, receptor tyrosine kinase)
Diseases named in the same sentence as KIT in open-access papers (continued):
Sharing a sentence is not in itself a finding about the gene and the disease.
glioma (continued). "We used specific FISH probes independently designed to recognise PDGFRA, KIT and VEGFR2 genes to determine the relative frequencies of gene amplification at chromosome 4q12 in our high grade glioma series." (PMID 23990986, 2013). "Finally, we combined the results of the XGB model and univariate Cox regression analysis to identify age, FGFR2, IDH1, CDK4, CDK6, KIT, and CDKN2A as crucial predictors of prognosis and OS time for glioma patients." (PMID 37273702, 2023). "However, the expression and prognosis of KIT, CHIC2, EXOC1, IGFBP7, RASL11B or USP46 in glioma are unclear." (PMID 36043552, 2023). "Consistent with this, high expression of the genes associated with PGC fate determination usually did not lead to poor outcomes of gliomas, such as KIT, DND1, NANOS3 and DDX4." (PMID 36435765, 2022). "Interestingly, both lines harboured genetic alterations reminiscent of high grade gliomas in humans - including the archetypal 4q12 amplification spanning PDGFRA and KIT in Res259, and PTEN deletion in Res186." (PMID 19365568, 2009).
soft tissue sarcoma (29 papers, 2007 to 2025). A malignant neoplasm arising from muscle tissue, adipose tissue, blood vessels, fibrous tissue, or other supportive tissues excluding the bones. "The rib metastasis, accompanied by a soft tissue mass resembling a primary soft tissue sarcoma, originated from a KIT exon 11-mutated colorectal GIST that had a protracted course of nearly two decades and was preceded via liver metastasis." (PMID 39199677, 2024). "GIST is a rare soft tissue sarcoma, for which KIT and DOG1 are used as highly sensitive diagnostic markers." (PMID 35804982, 2022). "Other small molecule inhibitors of c-KIT, such as Selinexor, Regorafenib, and Cabozantinib, have shown mixed results in different soft tissue sarcomas." (PMID 37681936, 2023). "GISTs are the most common soft tissue sarcoma of the gastrointestinal tract, resulting most commonly from KIT or platelet-derived growth factor receptor alpha (PDGFRalpha)-activating mutations." (PMID 26372813, 2015). "Employing HIER, the DAKO antibody showed reduced KIT staining in soft tissue sarcomas, however staining of GISTs remained unaffected with or without antigen retrieval." (PMID 22672386, 2012). "Overexpression of the PKCθ gene and PKCθ expression at the RNA level were also displayed in GIST samples but not in other c-KIT positive non-GIST soft tissue sarcomas or other tumors." (PMID 28915565, 2017). "In a study of 96 paediatric non-rhabdomyosarcoma soft tissue sarcomas, overexpression of PDGFR-α, PDGFR-β, VEGFR2 and c-KIT occurred in 32.3%, 17.7%, 19.8%, and 8.3% respectively." (PMID 40983796, 2025).
oncocytoma (28 papers, 2014 to 2025). "Tyrosine protein kinase (KIT) is overexpressed in various cancers, especially in ChRCC and oncocytoma." (PMID 34222474, 2021). "Claudin 8, paired box 8,20,21 and KIT overexpression in the oncocytoma-like regions further corroborated the tumor as being from a renal oncocytoma-like lineage." (PMID 25275525, 2014). "Although CK7 staining may not be beyond the expected level of oncocytoma, findings such as negative vimentin staining and positive KIT staining generally argue against other considerations, such as papillary or clear cell renal cell carcinoma with eosinophilic cells." (PMID 29090117, 2017). "Likewise, contrasting to oncocytoma and chromophobe RCC, which are typically positive for KIT, LOT shows a negative reaction." (PMID 39287823, 2024).
thyroid cancer (28 papers, 2012 to 2025). "These miRNAs target c-KIT and p27, which influence the cell cycle and contribute to thyroid cancer development." (PMID 41228195, 2025). "Let us analyze what measure of regulation is the most informative and use the examples of FOS and KIT (another gene down-regulated in thyroid cancer)." (PMID 32887258, 2020). "c-KIT overexpression in K1 thyroid cancer cells was confirmed by real time PCR, flow cytometric analysis and immunocytochemistry." (PMID 28301608, 2017). "We included in the model the expression of KIT (which has been shown to have the highest prediction value in our previous studies) as well as the TC-1 gene, which is related to thyroid cancer." (PMID 26581891, 2015). "Gene mutations were found in the NRAS, KRAS, BRAF, and KIT genes and were similar to those in thyroid carcinoma, but some patients (37.5%) did not exhibit any gene mutations." (PMID 33763376, 2021). "Taken together, those results provide evidence that CTC/miR-146/KIT axis might contribute to the progression of thyroid cancer." (PMID 32165673, 2020). "In thyroid carcinoma, lower levels of KIT positively correlate with more malignant phenotypes." (PMID 31703248, 2019). "This work aims to investigate the role of c-KIT expression in thyroid cancer, especially in PTC, which is still unknown." (PMID 28301608, 2017). "Taken together these results suggest that c-KIT overexpression may led to thyroid cancer cells regression of malignant features and tumor proliferation." (PMID 28301608, 2017). "Few papers have investigated the role of KIT in thyroid cancer as a possible new tumor marker." (PMID 26581891, 2015). "Thus, the same authors determined the diagnostic utility of a nine gene (KIT, SYNGR2, C21orf4, Hs.296031, DDI2, CDH1, LSM7, TC1, and NATH) assay to distinguish benign malignant thyroid neoplasms with a predictive power of 80 %." (PMID 26581891, 2015). "As miRNAs have been reported to be deregulated in thyroid cancer, and they have been shown to function both as tumor suppressors and oncogenes, we decided to assess the prediction value of two miRNAs targeting the KIT gene; namely, miR-146b and miR-222." (PMID 26581891, 2015). "Lenvatinib, a multitargeted kinase inhibitor of FGFR1–4, VEGFR1-3, KIT, RET, and PDGFR-β,4 has been proven effective for liver and thyroid cancers." (PMID 40747481, 2025). "The expression levels of CHEK1, c-KIT, SLC26A4, TG and TPO were significantly altered in all types of thyroid carcinomas." (PMID 27329729, 2016).
gastric cancer (26 papers, 2006 to 2026). A primary or metastatic malignant neoplasm involving the stomach. "Another alteration in KIT, the p.M541L, is a missense mutation resulting from A > C transversion at position 55593464 found in sample T4, was also detected in a patient with gastric cancer patient as reported in the ICGC’s portal." (PMID 25404506, 2014). "As such, KIT inhibitors, are currently being investigated in clinical trials for their therapeutic potential in gastric cancer.TXNIP functions primarily as a molecule that binds to TRX to regulate ROS and oxidative stress within cells." (PMID 40182050, 2025). "Hotspot mutations occurring in the codon 835 of the FLT3 oncogene have been implicated in the majority of AML and ALL patients, and recurrent aberrations such as D816V and V560D found in the KIT oncogene have been associated with patients suffering from AML and gastric cancer, respectively." (PMID 34068918, 2021). "Also, the poor correlation of other proteins and the tight relation with KIT provided a possibility that KIT regulated the levels of other survival-related proteins and worked together to affect the prognosis of stomach cancer." (PMID 29050270, 2017). "Moreover, two benzo[a]phenoxazines that showed high stability in the binding to the G4 in the KIT core promoter, with a preference for KIT2 over KIT1, were able to down-regulate KIT gene expression in human gastric carcinoma cells." (PMID 24108400, 2013). "Based on the regulation activity on reporter gene, we studied the effects of L-Apt12-6 on endogenous c-KIT expression in Human Gastric Cancer cell line (HGC-27), which has a high level of c-KIT expression." (PMID 37870474, 2023). "After screening for oncogenes or suppressor genes, KIT, KRAS, and ERBB2 were significantly higher in gastric cancer ECs." (PMID 35755820, 2022). "Except that SELE and KIT are not being studied in depth right now, we found several genes that were related to the prognosis and survival of gastric cancer patients." (PMID 34367971, 2021). "Yan reported that KIT and PDGFRA mutation analysis of gastric tumors, background gastric mucosa, and GIST in 15 cases, wherein gastric GIST was accidentally found in surgical specimens operated for gastric cancer, showed no genetic association." (PMID 33512639, 2021).
lymphoma (25 papers, 2007 to 2025). A malignant (clonal) proliferation of B- lymphocytes or T- lymphocytes which involves the lymph nodes, bone marrow and/or extranodal sites. "Five noninvasive biomarkers (FLT4, SFTPB, GNPTG, F5, and IL-17A) were further validated in an independent lymphoma cohort (n = 39), and another three noninvasive biomarkers (KIT, CCL3, and TNFSF1) were validated in NSCLC cohort (n = 76)." (PMID 38349411, 2024). "To address this question, we validated eight plasma proteins (IL-17A, F5, FLT4, SFTPB, and GNPTG in lymphoma, TNFSF12, CCL3, and KIT in NSCLC) for response prediction and three plasma proteins (IL36G, SERPINC1, and LTA) for relapse monitoring." (PMID 38349411, 2024). "This study found that immunotherapies such as cytokine-based therapies, ICIs such as mAbs, anti-KIT antibodies, and cellular therapies with mAbs are currently being used to treat GIST, adenocarcinoma subtype, and lymphoma." (PMID 37692610, 2023). "Compound 2 showed significant antiproliferative activity in a human lymphoma model, SU-DHL4, known to express substantial levels of c-KIT." (PMID 31590335, 2019). "Rather, KIT is routinely assessed by IHC as a diagnostic marker to distinguish between different cancer types, such as MCT (KIT IHC positive) versus lymphoma (KIT IHC negative), or GIST (KIT IHC positive) versus fibrosarcoma (KIT IHC negative)." (PMID 38787171, 2024). "However, based on the available literature, we assume that the lymphoma cells did not express KIT D816V, which is also supported by the fact that the “bystander MC” in the skin lesion did neither reveal atypical morphology or CD25 expression." (PMID 40913208, 2025).
ovarian tumor (25 papers, 2013 to 2025). "Collectively, these observations allow formulation of an innovative model in which SCF binds c-KIT expressed by ovarian tumor cells or infiltrating myeloid cells, resulting in IDO expression." (PMID 24302925, 2013). "Indeed, miR-551b upregulates STAT3 and c-KIT and enhances the resistance of ovarian tumor cells to anoikis." (PMID 27743201, 2016). "Multiple markers, such as the Hoechst side population, CD133+, CD117 (c-KIT)+, ALDH1+ or CD44+ cells, have been described and used to identify CSCs from ovarian tumors." (PMID 31159852, 2019). "One potential mechanism is that IDO activity may be driven by c-KIT signaling following binding of stem cell factor (SCF), which is secreted by ovarian tumors." (PMID 24302925, 2013).
adenoid cystic carcinoma (24 papers, 2007 to 2026). A malignant tumor arising from the epithelial cells. "c‐KIT mutations led to a significant decrease in MAPK activity in adenoid cystic cancer cells." (PMID 37506147, 2023). "The neoplastic population also showed strong expression of Bcl-2 and CD117 (c-KIT), two markers commonly associated with adenoid cystic carcinoma (AdCC), thereby supporting the diagnosis." (PMID 41133536, 2025). "KIT, a membrane tyrosine kinase receptor, is overexpressed in adenoid cystic carcinoma and can be detected by immunohistochemistry." (PMID 37383158, 2023). "Meta-analysis revealed an outstanding discriminative ability of c-KIT for adenoid cystic carcinoma (AdCC) over polymorphous adenocarcinoma [P(LG)A] but did not confirm the prognostic significance of stem cell markers in MSGTs." (PMID 39858584, 2024). "Cellular pleomorphic adenomas presented with basaloid features were evaluated with p63 and c‐KIT markers to rule out adenoid cystic carcinoma." (PMID 35092649, 2022). "According to two phase II trials that applied imatinib in patients with KIT-positive adenoid cystic cancers of salivary glands, imatinib was not of significant clinical benefit and the best observed response was a stable disease (SD)." (PMID 33296026, 2021). "All 4 adenoid cystic carcinomas cluster together in branch III and 5/7 of the apocrine tumors cluster together in branch V. All 18 tumors in branch II are positive for KRT5/6 staining, 97% of the tumors in branch I are EGFR negative, and all 14 tumors in branch V are KIT negative." (PMID 17910759, 2007).
anemia (24 papers, 2013 to 2025). A reduction in the number of red blood cells, the amount of hemoglobin, and/or the volume of packed red blood cells. "Deficiency of KIT function causes lethal anemia, leading to prenatal or perinatal mortality." (PMID 41007912, 2025). "Accordingly, we have identified EMP expansion and erythroid differentiation from EMP-derived progenitors in the fetal liver as the first events in which KIT acts to prevent severe anemia." (PMID 34395414, 2021). "Because cell components were different between WT and CALM−/− KIT+ fraction, that is, the erythroid progenitor fraction was larger in CALM−/− KIT+ fraction due to anemia than in WT KIT+ fraction (36.1% vs. 17.6%)." (PMID 25279552, 2014). "However, whether the lethal is due to anemia in the embryonic stage as previously found in a KIT defect mouse model needs to be further validated." (PMID 32194624, 2020). "We conclude that KIT expression in ECs of developing organs does not reflect an obvious functional role in tissue vascularisation at midgestation, prior to embryonic anaemia, but that vascular anomalies appear in late-stage embryos concurrent with emerging anaemia." (PMID 35416527, 2022).
angiosarcoma (24 papers, 2006 to 2025). A malignant tumor arising from the endothelial cells of the blood vessels. "Among the genes historically linked to hemangiosarcoma, alterations in CDKN2A/B, KDR, MYC, and KIT were prominently identified in our study, underscoring their potential roles in the pathogenesis of this cancer in dogs." (PMID 39872607, 2024). "In our exploration of the genetic landscape of canine hemangiosarcoma, we focused on identifying copy number alterations (CNAs) within genes previously associated with the disease, including CDKN2A/B, VEGFA, KDR, SKI, MYC, and KIT." (PMID 39872607, 2024). "Furthermore, our CNA analysis identified significant genomic regions linked to hemangiosarcoma pathogenesis, such as alterations in CDKN2A/B, VEGFA, KDR, MYC, and KIT." (PMID 39872607, 2024). "Kaposi's sarcoma must also be differentiated from angiosarcoma due to its similar histological features and IHC staining patterns; however, the patient population is typically associated with HIV and has immunopositivity for CD-117 (KIT) and CD-34 markers." (PMID 37113364, 2023). "Comparison of somatic copy number aberration profiles in human angiosarcoma and canine hemangiosarcoma identified recurrent copy number gains in KDR (31% in human, 22% in canine) and KIT (17% in both)." (PMID 32571313, 2020). "In humans, KIT is often expressed in angiosarcomas, but it is not detected in most benign vascular tumors, and KIT positivity is more likely related to an immature phenotype." (PMID 27422008, 2016). "Recurrent gains of a small region of chromosome 4q12 containing KIT and VEGFR2 genes have been reported in sporadic angiosarcomas, and overexpression of vascular endothelial growth factors and their receptors have been linked with the good response of these tumors to sunitinib." (PMID 26474454, 2015).
asthma (24 papers, 2013 to 2025). "Indeed, KIT, implicated in the human “Th2 high” asthma endotype, has recently been advocated as an appropriate therapeutic target molecule in cases of severe refractory asthma (e.g., imatinib or anti-KIT monoclonal antibodies)." (PMID 39594673, 2024). "Imatinib, a KIT inhibitor that inhibits tryptase release from mast cells, is attracting attention in the field of clinical medicine for severe asthma but remains to be developed." (PMID 40142115, 2025). "They showed increased levels of IL‐17+KIT+ ILC2s in the sputum of severe asthma patients, which correlated with neutrophilic inflammation." (PMID 40016948, 2025). "KIT, validated here using qPCR results, is also found to play an important role in lung hypersensitivity, fibrosis, and the Th2-high human asthma endotype." (PMID 39594673, 2024). "Accumulating evidence shows that ITGB4, SEMA3D, FCAR (Fc fragment of IgA receptor), KIT (KIT proto-oncogene, receptor tyrosine kinase), PGLYRP1, IL17RB, BIRC5 and PTGS1 are associated with prognosis in asthma." (PMID 36837510, 2023). "KIT is the receptor for stem cell factor; soluble stem cell factor levels are increased in the serum of asthmatics and correlate with asthma severity." (PMID 33805900, 2021). "In a randomized clinical trial repurposing imatinib, a tyrosine kinase inhibitor of the KIT proto-oncogene receptor tyrosine kinase, for severe asthma, imatinib use improved forced expiratory volume in 1 s (FEV1) compared to placebo treatment." (PMID 33805900, 2021). "For example, barzolvolimab, a monoclonal antibody against KIT, has been shown to be effective in chronic prurigo and chronic urticaria, and imatinib, a KIT inhibitor, can reduce airway hyperresponsiveness in patients with severe asthma through mast cell depletion." (PMID 40131162, 2025). "Furthermore it can be inhibited by the drug Imatinib, an inhibitor of the tyrosine kinase activity of KIT, which decreases mast cell function and improves lung function in severe asthma." (PMID 28787016, 2017). "Finotto and others found that the ligand of KIT, stem cell factor (SCF), played a critical role in a murine asthma model." (PMID 34336929, 2021). "MiR-146-5p targets inflammatory mediators like COX2, IL-1β, KIT, NFKB1, TLR4, TRAF6, and UHRF1 and has been proposed as a predictor for asthma exacerbations in childhood asthma." (PMID 32998415, 2020). "Strong connections between c-KIT and CAD in dogs, as well as psoriasis and asthma in humans has also been reported." (PMID 28570617, 2017). "Downstream analysis identified the top 10 epithelial RNAs: hsa_circ_0001585, hsa_circ_0078031, hsa_circ_0000552, miR-30a-3p, miR-30d-3p, KIT, CD69, ADRA2A, BPIFA1, and GGH, demonstrating the utility of the epithelial circRNA-miRNA-mRNA network in understanding the pathogenesis of asthma." (PMID 36459329, 2022).
myeloma (24 papers, 2012 to 2025). "c-Kit is functionally expressed in 30% of MM patients, and imatinib, whose primary target is c-KIT, inhibited the proliferation of myeloma cells in vitro." (PMID 36555805, 2022). "Because amuvatinib also impairs KIT and PDGFR signaling, we tested impact of imatinib (an established KIT and PDGFR inhibitor) in myeloma cells." (PMID 24326130, 2013). "On the other hand, a markedly better outcome has already been demonstrated in tumors that expressed c-KIT compared with those that did not, such as neuroblastomas, nasopharyngeal carcinomas and multiple myeloma." (PMID 22839358, 2012).